PNLIP (pancreatic lipase)
Diseases named in the same sentence as PNLIP in open-access papers (continued):
Sharing a sentence is not in itself a finding about the gene and the disease.
kidney disease (2 papers, 2021 to 2022). "Our results contradict those of the only other study investigating the association between serum feline pancreatic lipase concentrations and kidney disease in cats." (PMID 34738673, 2021). "In that study, the effect of azotemia and naturally occurring kidney disease (as defined by increased serum creatinine concentrations and urine specific gravity <1.035) on serum feline pancreatic lipase was investigated in 2189 samples." (PMID 34738673, 2021). "Given the molecular weight of pancreatic lipase and a lack of a consistent relationship between pancreatic lipase and creatinine concentration, it is suspected that changes in GFR alone are not responsible for increased Spec cPL concentrations in dogs with renal disease." (PMID 35739917, 2022).
liver (1 paper, 2016). "Because alcoholic liver and pancreas damage are characterized by changes in certain circulating markers we examined AST/GOT, ALT/GPT, GGT, pancreatic α-amylase, and pancreatic lipase levels in patients and their degree of association with chemokine concentrations." (PMID 28149283, 2016).
PNLIP also shares sentences with these, for which no sentence is quoted: cardiovascular disease (3 papers); acute renal failure (2); Alzheimer disease (2); bladder cancer (2); chronic kidney disease (2); Hepatic steatosis (2); Hypertension (2); infection (2); pancreatic duct adenocarcinoma (2); T-cell leukemia (2); Abdominal obesity (1); acute myeloid leukemia (1); alcohol addiction (1); anorexia nervosa (1); breast carcinoma (1); cholecystolithiasis (1); cholestasis (1); colon adenocarcinoma (1); colorectal adenocarcinoma (1); cystic fibrosis (1); dilatation (1); electrolyte imbalance (1); enteropathy (1); gallbladder disease (1); gastritis (1); gastroenteritis (1); Glucose intolerance (1); glucose metabolism disorders (1); hypoparathyroidism (1); infectious disease (1).
A further 12 diseases each share a sentence with PNLIP in 1 paper.